RACGAP1 (Rac GTPase activating protein 1)
Description:
Component of the centralspindlin complex that serves as a microtubule-dependent and Rho-mediated signaling required for the myosin contractile ring formation during the cell cycle cytokinesis. Required for proper attachment of the midbody to the cell membrane during cytokinesis. Sequentially binds to ECT2 and RAB11FIP3 which regulates cleavage furrow ingression and abscission during cytokinesis. Plays key roles in controlling cell growth and differentiation of hematopoietic cells through mechanisms other than regulating Rac GTPase activity. Has a critical role in erythropoiesis. Also involved in the regulation of growth-related processes in adipocytes and myoblasts. May be involved in regulating spermatogenesis and in the RACGAP1 pathway in neuronal proliferation. Shows strong GAP (GTPase activation) activity towards CDC42 and RAC1 and less towards RHOA. Essential for the early stages of embryogenesis. May play a role in regulating cortical activity through RHOA during cytokinesis. May participate in the regulation of sulfate transport in male germ cells.
Synonyms: MgcRacGAP; CYK4; HsCYK-4; CDAN3B; ID-GAP; RCGAP1
Tractability: Small molecule: a structure with a bound ligand is known. Antibody: UniProt places it where antibodies can reach, with medium confidence; its Gene Ontology location is reachable by antibodies, with medium confidence. PROTAC: UniProt records ubiquitination sites on it; ubiquitination databases record sites on it.
Gene: Protein-coding gene on chromosome 12 (49,976,923 to 50,033,136, reverse strand). Ensembl gene ENSG00000161800.
Subcellular location: Nucleus; Cytoplasm; Cytoplasm, cytoskeleton, spindle; Cytoplasmic vesicle, secretory vesicle, acrosome; Cleavage furrow; Midbody, Midbody ring; Cell membrane; Midbody
Subcellular location (Human Protein Atlas): Nucleoplasm
Pathways (Reactome):
Signal Transduction: CDC42 GTPase cycle; RAC1 GTPase cycle; RAC2 GTPase cycle; RAC3 GTPase cycle; RHOA GTPase cycle; RHOB GTPase cycle; RHOC GTPase cycle; RHOD GTPase cycle
Hemostasis: Kinesins
Immune System: MHC class II antigen presentation
Vesicle-mediated transport: COPI-dependent Golgi-to-ER retrograde traffic
Gene Ontology:
Molecular function: alpha-tubulin binding; beta-tubulin binding; gamma-tubulin binding; GTPase activator activity; microtubule binding; phosphatidylinositol-3,4,5-trisphosphate binding; protein binding; protein kinase binding; protein-macromolecule adaptor activity
Biological process: actomyosin contractile ring assembly; erythrocyte differentiation; mitotic cytokinesis; mitotic spindle midzone assembly; positive regulation of cytokinesis; regulation of attachment of spindle microtubules to kinetochore; spermatogenesis; sulfate transmembrane transport; neuroblast proliferation; regulation of embryonic development; regulation of small GTPase mediated signal transduction; Rho protein signal transduction; cell differentiation; signal transduction
Cellular component: centralspindlin complex; cleavage furrow; cytoplasmic side of plasma membrane; extracellular exosome; midbody; mitochondrion; mitotic spindle; nucleoplasm; nucleus; spindle; spindle midzone; cytosol; acrosomal vesicle; cytoplasm; Flemming body; plasma membrane
Genetic constraint (gnomAD): Loss-of-function variants: 26 observed, 69.11 expected, observed/expected ratio (o/e) 0.38, 90% interval 0.28 to 0.52. The upper end of that interval is the gene's LOEUF score, 0.52, which puts it in group 2 of 6, group 1 being the genes least tolerant of losing a copy. Missense variants: 563 observed, 774.67 expected, observed/expected ratio (o/e) 0.73, 90% interval 0.68 to 0.78. Synonymous variants: 224 observed, 267.76 expected, observed/expected ratio (o/e) 0.84, 90% interval 0.75 to 0.94.
Homologues: Orthologues: chimpanzee RACGAP1 (99% identical), macaque RACGAP1 (99% identical), dog RACGAP1 (96% identical), pig RACGAP1 (96% identical), rabbit RACGAP1 (96% identical), guinea pig RACGAP1 (94% identical), mouse Racgap1 (84% identical), rat Racgap1 (83% identical), tropical clawed frog racgap1 (76% identical), zebrafish racgap1 (67% identical), Drosophila melanogaster tum (33% identical), Caenorhabditis elegans cyk-4 (28% identical), and 3 more.
Diseases named in the same sentence as RACGAP1 in open-access papers:
RACGAP1 is named in the same sentence as 71 diseases in open-access papers, as found by Europe PMC text mining. Sharing a sentence is not in itself a finding about the gene and the disease. The quoted sentences say what the papers report.
breast carcinoma (46 papers, 2013 to 2025). "Consistently with these findings, our current study also identified RACGAP1 as an oncogene in breast cancer, associated with poor survival in breast cancer." (PMID 41444950, 2025). "RACGAP1 was up-regulated in breast cancer, and its high expression was associated with worse survival outcome of patients, identified as risk factor in breast cancer." (PMID 41444950, 2025). "In breast cancer, overexpression of RACGAP1 was frequently linked to a high tendency of nipple invasion, lymph node/distant metastasis, and an advanced TNM stage and worse survival outcomes." (PMID 41444950, 2025). "RACGAP1 was highly expressed in breast cancer, and associated with poor prognosis and ferroptosis activity." (PMID 41444950, 2025). "Finding of this study will contribute us to understand the dysregulation and the prognosis associations of RACGAP1 in breast cancer in clinic." (PMID 41444950, 2025). "High expression of RACGAP1 in basal-like breast cancer is usually associated with poor prognosis and high recurrence rates." (PMID 38898473, 2024). "The RacGAP1 gene is significantly upregulated in a variety of malignancies and is linked to a higher rate of tumor metastasis and a poor prognosis in breast cancer patients." (PMID 36192752, 2022). "The clinical correlation pathological study of RACGAP1, IRF7, and DMD showed that RACGAP1 was highly expressed in the high-risk group, indicating that RACGAP1 has a greater impact on patients with breast cancer infected with SARS-CoV-2." (PMID 36060002, 2022). "Analysis of feature importance of the trained classifiers on the top 44 genes of PC1 for the LumA versus LumB comparison determined RACGAP1, a putative oncogene in breast cancer, to be associated with the highest averaged information ranking." (PMID 34179840, 2021). "Based on analysis of TCGA database, high expression of RACGAP1 is significantly associated with breast cancer, lung adenocarcinoma, papillary renal cell carcinoma, hepatocellular carcinoma and cutaneous melanoma." (PMID 30866526, 2019). "In a study of high-risk breast cancer patients treated with postoperative dose-dense chemotherapy, it was shown that high RACGAP1 mRNA expression was of adverse prognostic significance in terms of DFS and OS." (PMID 27695115, 2016). "However, several studies showed increased RACGAP1 expression as a marker of cell division in breast cancer and a diagnostic marker in the early stages." (PMID 35928368, 2022). "In a clinical study, RACGAP1 mRNA expression was measured in high-risk breast cancer patients." (PMID 36200070, 2022). "Notably, depletion of ARHGAP11A in basal-like breast cancer cells was shown to lead to cell-cycle arrest mediated by p27 while depletion of RacGAP1 led to an increase in p21 protein associated with an increase in senescence." (PMID 34493786, 2021). "Besides, RACGAP1 was also considered as a poor prognosis marker in high‐risk early breast cancer." (PMID 33252198, 2021). "RACGAP1 is a key regulator in various cancers, like colorectal cancer, ovarian cancer, and breast cancer." (PMID 39908244, 2025). "To explore the roles of RACGAP1 in breast cancer, we successfully silenced or overexpressed its expression in both MDA-MB-231 and 4T1 cells." (PMID 41444950, 2025). "Altogether, these results suggested that RACGAP1 silencing sensitizes breast cancer ferroptosis by regulating CPT1A-dependent FA metabolism." (PMID 41444950, 2025). "Validation using UALCAN, GEPIA, and Kaplan-Meier plotters revealed that three key genes-RACGAP1, SPAG5, and KIF20A-were significantly overexpressed and associated with poor prognosis in breast cancer (BC), as well as advanced tumor staging." (PMID 39988630, 2025). "RACGAP1 also enhances the self-renewal, tumorigenicity, and metastatic potential of breast cancer stem cells." (PMID 41009526, 2025). "In this study, based on several transcriptome datasets, we identified Rac GTPase Activating Protein 1 (RACGAP1) as an oncogenic gene in breast cancer." (PMID 41444950, 2025).
breast carcinoma (continued). "A five-gene SLE prognostic signature (RACGAP1, HMMR, TTK, TOP2A, and KIF15) effectively stratified breast cancer survival risk." (PMID 40567613, 2025). "We found that RACGAP1 silencing markedly reduced the expression of CPT1A in breast cancer cell lines, while RACGAP1 overexpression enhanced the CPT1A expression." (PMID 41444950, 2025). "It has been reported that overexpression of RACGAP1 plays a crucial role in tumor metastasis and drives metastasis in breast cancer." (PMID 40586163, 2025). "In pancreatic ductal adenocarcinoma and breast cancer, miR-204-5p was downregulated, while RACGAP1, as the target of miR-204-5p, was upregulated." (PMID 39858398, 2024). "RACGAP1P accelerates breast cancer invasion and metastasis via miR-345-5p/RacGAP1 axis-mediated mitochondrial fission." (PMID 38405130, 2024). "RACGAP1 has also been shown to drive breast cancer metastasis by regulating ECT2-dependent mitochondrial quality control." (PMID 38468345, 2024). "Based on the data from The Cancer Genome Atlas (TCGA), RACGAP1 is one of the genes related to breast cancer prognosis." (PMID 39858398, 2024). "In related studies of breast cancer, it was found that high expression of RACGAP1 was significantly correlated with high histological grade and high NPI." (PMID 37196108, 2023). "Regarding its role in breast cancer progression, RACGAP1 was able to modulate ECT2-dependent mitochondrial quality control to drive breast cancer metastasis." (PMID 36430577, 2022). "Elevated RACGAP1 expression has been recorded in various cancers, including hepatocellular carcinoma, basal-like breast cancer, and gallbladder cancer." (PMID 35013128, 2022). "In breast cancer, RACGAP1 mRNA is expressed higher in tumorigenic tissue in comparison to normal tissue, and higher expression of RACGAP1 leads to a worse overall survival." (PMID 35356277, 2022). "RACGAP1 has been identified as a prominent activator of tumor invasion and metastasis in various cancers, including uterine carcinosarcoma, breast cancer, and ovarian cancer." (PMID 35340220, 2022). "In conclusion, lncRNA RACGAP1P promotes breast cancer invasion and metastasis via miR‐345‐5p/RACGAP1 pathway‐mediated mitochondrial fission." (PMID 33252198, 2021). "Co‐expression analysis of 460 breast cancer microarray data from TCGA dataset showed that RACGAP1P expression level positively correlated with its parental gene RACGAP1 at the transcription level (R = 0.74, P < 0.01)." (PMID 33252198, 2021). "Kehan confirmed that RACGAP1 played an essential role in breast cancer metastasis by modulating ECT2-dependent mitochondrial quality control." (PMID 34336648, 2021). "Herein, using microarray analysis, we revealed that the lncRNA RACGAP1P, the pseudogene of Rac GTPase activating protein 1 (RACGAP1), was up‐regulated in breast cancer tissues." (PMID 33252198, 2021). "The expressions of KIF4A, RACGAP1, CKS2, SHCBP1, and HMMR were high in breast cancer, associated with poor OS and different breast cancer subclasses." (PMID 33959662, 2021). "A recent study on breast cancer revealed that RACGAP1 promotes mitochondrial dynamic driven metastasis through recruiting ECT2 and subsequently activating ERK-DRP1 pathway." (PMID 34239347, 2021). "Then, we further clarified the regulatory mechanism of RACGAP1P in breast cancer metastasis induced by mitochondrial fission in a miR‐345‐5p/RACGAP1‐dependent manner." (PMID 33252198, 2021). "In basal-like breast cancer, depletion of RACGAP1 impaired cell growth via partly resulting from p21-induction and onset of senescence." (PMID 34239347, 2021). "RACGAP1 inhibits cell migration in Basal-like Breast Cancer cell lines, while ARHGAP11A promotes it42." (PMID 32728097, 2020). "RacGAP1 regulates the activation of Rho GTPase, which is reported to drive tumor growth and to act as an oncogene in basal-like breast cancers." (PMID 31426369, 2019).
breast carcinoma (continued). "The expressions of cyclin D1, TOP2A, and RacGAP1 were found to be slightly up-regulated in the primary breast cancer cell samples treated with E2." (PMID 31293425, 2019). "Rho GTPase transcriptome analysis also revealed oncogenic roles for RacGAP1 in basal-like breast cancers." (PMID 30545369, 2018). "It has been shown that the RACGAP1 gene encodes Rac GTPase activating protein 1 (RACGAP1), which plays a role in cell proliferation, motility, invasion and metastasis of breast cancer cells." (PMID 27695115, 2016). "In the present study, we sought to develop a risk for recurrence score (RRS) based on three proliferation markers, e.g. RACGAP1, TOP2A and Ki67, in high-risk early breast cancer patients and evaluate its ability to predict risk for relapse and death." (PMID 27695115, 2016). "In the present study, we developed a risk for recurrence score (RRS), based on mRNA expression of two proliferation markers (RACGAP1 and TOP2A), in high-risk early breast cancer patients and evaluated its ability to predict risk for relapse and death." (PMID 27695115, 2016). "Mice in sh-RACGAP1 possessed smallest tumor volume and tumor weight than control and sh-NC groups, indicating RACGAP1 silencing could observably inhibit breast cancer growth in vivo." (PMID 41444950, 2025). "RACGAP1 is identified as an oncogenic gene in breast cancer." (PMID 41444950, 2025). "In breast cancer, RACGAP1 promotes cancer cell metastasis by regulating mitochondrial mass thereby." (PMID 38167018, 2024). "In the genital system, RACGAP1 overexpression is detected, particularly in breast cancer." (PMID 39858398, 2024). "RACGAP1 can be involved in the regulation of breast cancer metastasis by targeting ECT249." (PMID 37391503, 2023). "A prognostic SLEscore consisting of five SLE-related genes (RACGAP1, HMMR, TTK, TOP2A, and KIF15) could distribute patients with breast cancer into the high- and low-risk groups according to survival rates with good predictive ability (p < 0.05)." (PMID 36726984, 2022). "RACGAP1 modulates mitochondrial quality control to drive breast cancer metastasis." (PMID 36726984, 2022). "Previous studies showed that elevated expression of RacGAP1 has been observed in several human cancers including breast cancer, melanoma, hepatocellular cancer, gastric cancer, head and neck squamous cell cancer (HNSCC), meningioma, etc. and linked with poor prognosis." (PMID 35831303, 2022). "RACGAP1 was initially identified in testis and male germ cells and has been demonstrated to be a key regulator in various malignancies, such as colorectal cancer, ovarian cancer, meningioma, uterine cancer, and breast cancer." (PMID 35445033, 2022). "Few studies have been performed on RACGAP1 and breast cancer." (PMID 35928368, 2022). "Mechanistically, the enhancement of mitochondrial fission by RACGAP1P relied on its competitive targeting of miR-345-5p, causing the activation of Drp1, which revealed that lncRNA RACGAP1P facilitates breast cancer metastasis through miR-345-5p/RACGAP1 axis-mediated mitochondrial fission." (PMID 36192752, 2022). "Further experiments showed that the overexpression of RACGAP1P could enhance mitochondrial fission by up‐regulating its parental gene RACGAP1 via competitively binding to miR‐345‐5p and thus increase the invasive ability of breast cancer cells." (PMID 33252198, 2021). "As pseudogenes are highly possible to function through their parental genes, we hypothesized that RACGAP1 facilitated breast cancer cell invasion by inducing mitochondrial fragmentation." (PMID 33252198, 2021). "In conclusion, overexpression of lncRNA RACGAP1P could enhance mitochondrial fission by competitive binding with miR‐345‐5p against its parental gene RACGAP1, thus enhancing the invasive and metastatic ability of breast cancer cells." (PMID 33252198, 2021). "Also, the knockdown of RacGAP1 was shown to limit cell proliferation and to promote senescence in basal-like breast cancer cells." (PMID 31200451, 2019).